BTBD7 (BTB domain containing 7)
Description:
Acts as a mediator of epithelial dynamics and organ branching by promoting cleft progression. Induced following accumulation of fibronectin in forming clefts, leading to local expression of the cell-scattering SNAIL2 and suppression of E-cadherin levels, thereby altering cell morphology and reducing cell-cell adhesion. This stimulates cell separation at the base of forming clefts by local, dynamic intercellular gap formation and promotes cleft progression (By similarity).
Synonyms: FLJ10648; FUP1
Tractability: PROTAC: ubiquitination databases record sites on it.
Gene: Protein-coding gene on chromosome 14 (93,237,550 to 93,333,092, reverse strand). Ensembl gene ENSG00000011114.
Subcellular location: Nucleus
Subcellular location (Human Protein Atlas): Focal adhesion sites
Gene Ontology:
Biological process: regulation of branching involved in salivary gland morphogenesis; morphogenesis of a branching epithelium
Cellular component: nucleus
Genetic constraint (gnomAD): Loss-of-function variants: 40 observed, 96.1 expected, observed/expected ratio (o/e) 0.42, 90% interval 0.32 to 0.54. The upper end of that interval is the gene's LOEUF score, 0.54, which puts it in group 2 of 6, group 1 being the genes least tolerant of losing a copy. Missense variants: 1,137 observed, 1,415.7 expected, observed/expected ratio (o/e) 0.8, 90% interval 0.76 to 0.84. Synonymous variants: 509 observed, 524.55 expected, observed/expected ratio (o/e) 0.97, 90% interval 0.9 to 1.04.
Homologues: Orthologues: chimpanzee BTBD7 (99% identical), macaque BTBD7 (99% identical), dog BTBD7 (96% identical), pig BTBD7 (96% identical), rat Btbd7 (95% identical), guinea pig BTBD7 (94% identical), mouse Btbd7 (93% identical), rabbit BTBD7 (92% identical), tropical clawed frog btbd7 (84% identical), zebrafish btbd7 (67% identical), Drosophila melanogaster CG16952 (34% identical), Caenorhabditis elegans C39F7.5 (17% identical).
Diseases named in the same sentence as BTBD7 in open-access papers:
BTBD7 is named in the same sentence as 16 diseases in open-access papers, as found by Europe PMC text mining. Sharing a sentence is not in itself a finding about the gene and the disease. The quoted sentences say what the papers report.
lung carcinoma (4 papers, 2014 to 2023). "Although we focused on the role of HEG1 as an effector for IGF2BP1 function in OXA resistance, BTBD7 may be also involved in OXA resistance as it has been implicated in chemoresistance in lung Carcinoma A549 Cells54." (PMID 37024475, 2023). "This study aimed to investigate the relationship between BTBD7 and E-cadherin in lung cancer and explore the role of BTBD7 in EMT." (PMID 31886230, 2019). "In summary, we found that BTBD7 is highly expressed in lung cancer tissues and A549 cells and induces EMT mainly by downregulating E-cadherin and upregulating N-cadherin, vimentin, and FN." (PMID 31886230, 2019). "Immunohistochemical analysis showed significantly larger regions with positive BTBD7 staining in lung cancer tissues than in paracancer tissues." (PMID 31886230, 2019). "The western blot results showed that BTBD7 showed a tendency toward high expression during the process of EMT in lung cancer cells." (PMID 31886230, 2019). "Overexpression of BTBD7 in lung cancer cells demonstrated a significant downregulation of E-cadherin expression and upregulated expression of EMT markers in vivo." (PMID 31886230, 2019). "BTBD7 is expressed at a high level during the development and metastasis of lung cancer and inhibits the expression of E-cadherin and promotes EMT in lung cancer." (PMID 31886230, 2019). "After transfection of lung cancer cells with BTBD7-siRNA, the expression of E-cadherin was upregulated, and the cell migration ability was decreased." (PMID 31886230, 2019). "All experimental results showed that the levels of BTBD7, N-cadherin, fibronectin, and vimentin were increased in lung cancer tissues and cells, while the E-cadherin level was decreased." (PMID 31886230, 2019). "The relative protein levels of BTBD7 (0.45 ± 0.16), FN (0.81 ± 0.24), and vimentin (0.42 ± 0.21) in lung cancer tissues were significantly higher (p < 0.05) than those in paracancer tissues (0.20 ± 0.09, 0.26 ± 0.16, and 0.15 ± 0.13, respectively)." (PMID 31886230, 2019). "Fresh lung cancer and paracancer tissue specimens were collected from 30 patients, and the expression of BTBD7, E-cadherin, N-cadherin, fibronectin, and vimentin was analyzed by qRT-PCR, western blotting, and immunohistochemistry." (PMID 31886230, 2019). "In vitro experiments were performed using siRNA to investigate the function of Btbd7 in lung cancer cells." (PMID 25253020, 2014). "We used siRNA to downregulate Btbd7 expression in lung cancer cells in vitro to investigate its possible function." (PMID 25253020, 2014). "Downregulation of Btbd7 expression in lung cancer cells by siRNA significantly inhibits cancer cell invasion and effectively restores E-cadherin expression in cancer cell membrane." (PMID 25253020, 2014). "We further demonstrated that Btbd7 expression was required for lung cancer cell invasion through regulating E-cadherin." (PMID 25253020, 2014). "We used NCI-H1299 cells with higher level of Btbd7 expression to perform in vitro study to investigate the function of Btbd7 in lung cancer cells." (PMID 25253020, 2014). "The wound healing assay demonstrated that the migration of A549 lung cancer cells was regulated by BTBD7 and that targeted interference with BTBD7 could affect the metastasis of lung cancer cells." (PMID 31886230, 2019). "Moreover, in lung cancer, BTBD7 is localized mainly in the cytoplasm; thus, it likely downregulates E-cadherin through regulation of protein levels." (PMID 31886230, 2019). "All clinical, cell-based, and animal experiments demonstrated the same results; thus, BTBD7 may be an important therapeutic target in lung cancer." (PMID 31886230, 2019). "In addition, we used specific siRNA to downregulate Btbd7 expression to investigate its possible function to impact E-cadherin expression and invasion ability in lung cancer cells in vitro." (PMID 25253020, 2014).
lung carcinoma (continued). "In conclusion, our study provides evidence that Btbd7 contributes to lung cancer cell invasion and metastasis through regulating E-cadherin expression and may be a promising cancer marker." (PMID 25253020, 2014). "Moreover, the migration capacity of lung cancer cells was increased by the high level of BTBD7." (PMID 31886230, 2019). "Therefore, we hypothesized that BTBD7 can downregulate E-cadherin and promote EMT in lung cancer cells and that it is linked to the development of lung cancer." (PMID 31886230, 2019). "BTBD7 plays essential roles in lung cancer metastasis, but the mechanisms remain unknown." (PMID 31886230, 2019). "However, expression and function of Btbd7 in malignant tumors including lung cancer are largely unknown so far." (PMID 25253020, 2014). "The pathological analysis shows that overexpression of Btbd7 in non-small cell lung cancer was associated with lymph node metastasis and advanced TNM stages, suggesting that Btbd7 may be an important molecule to promote the malignant phenotype of lung cancer." (PMID 25253020, 2014). "We concluded that BTBD7 is highly expressed during lung cancer development and metastasis and can inhibit the expression of E-cadherin and promote EMT in lung cancer." (PMID 31886230, 2019). "All tumors in the BTBD7-ENTER group were larger than those in the p-ENTER group, indicating that BTBD7 enhanced the development of lung cancer." (PMID 31886230, 2019). "For example, BTBD7 down-regulated E-cadherin and promoted EMT in lung cancer." (PMID 35281866, 2022). "However, it is still not clear whether Btbd7 is also involved in the process of invasion and metastasis of lung cancer cells." (PMID 25253020, 2014).
non-small cell lung carcinoma (2 papers, 2014 to 2020). A group of at least three distinct histological types of lung cancer, including non-small cell squamous cell carcinoma, adenocarcinoma, and large cell carcinoma. "Btbd7 expression was elevated in non-small cell lung cancer tissues compared to normal lung tissues." (PMID 25253020, 2014). "Immunohistochemistry and Western blotting were used to investigate Btbd7 expression in non-small cell lung cancer and lung tissues." (PMID 25253020, 2014). "The aim of this study is to investigate the clinicopathological significance and possible function of Btbd7 in non-small cell lung cancer." (PMID 25253020, 2014). "Btbd7 contributes to reduced expression of E-cadherin and may be a promising cancer marker in non-small cell lung cancer." (PMID 25253020, 2014).
brain tumor (1 paper, 2022). "Other studies described BTBD7 as a cell growth suppressor protein (ZNF238 is expressed in postmitotic brain cells and inhibits brain tumor growth) and a promotor of angiogenesis." (PMID 35986427, 2022).
hepatocellular carcinoma (1 paper, 2018). A malignant tumor that arises from hepatocytes. "BTBD7 enhanced hepatocellular carcinoma (HCC) angiogenesis and metastasis, hence, promoting HCC progression." (PMID 30001383, 2018).
leukoplakia (1 paper, 2014). A white patch or plaque on a mucous membrane that cannot be characterized clinically or pathologically as any other disease. "Amplification of BTBD7, KHDRBS1, PARP1 and RAB1A was exclusively detected in progressive leukoplakia and corresponding OSCC." (PMID 24403051, 2014). "Amplified genes mapping within recurrent CNAs (KHDRBS1, PARP1, RAB1A, HBEGF, PAIP2, BTBD7) were selected for validation, by quantitative real-time PCR, in an independent set of 32 progressive leukoplakia, 32 OSSCs and 21 non-progressive leukoplakia samples." (PMID 24403051, 2014). "BTBD7, KHDRBS1, PARP1 and RAB1A were all found to be amplified in progressive leukoplakia lesions and OSSCs and not amplified in non-progressive leukoplakia." (PMID 24403051, 2014).
liver cancer (1 paper, 2020). An epithelial or non-epithelial malignant neoplasm that arises from the liver. "BTBD7, a BTB/POZ domain-containing protein, was first shown the correlation with cell proliferation and tumor formation in liver cancer." (PMID 33108235, 2020).
lymph node metastasis (1 paper, 2014). "Increased Btbd7 expression was significantly associated with lymph node metastasis, reduced E-cadherin expression and patients’ poor clinical outcome." (PMID 25253020, 2014). "Increased Btbd7 expression in NSCLC was significantly associated with histological type, lymph node metastasis and TNM stages (p < 0.05)." (PMID 25253020, 2014). "Multivariate analysis shows that lymph node metastasis, TNM stage and Btbd7 expression are independent prognostic markers for NSCLC (p < 0.05)." (PMID 25253020, 2014). "Btbd7 expression was higher in cases with lymph node metastasis than those without lymph node metastasis (p < 0.05)." (PMID 25253020, 2014). "In this study, our findings suggest that the elevated expression of Btbd7 was a common abnormality in NSCLC compared to non-tumor portion and could play a role in NSCLC development including lymph node metastasis and thus contribute to patients’ poor outcome." (PMID 25253020, 2014).
preeclampsia (1 paper, 2019). Preeclampsia is a hypertensive disorder of pregnancy that is characterized by new-onset hypertension with proteinuria presenting after 20 weeks of gestation, and depending on mild or severe forms may initially present with severe headache, visual disturbances, and hyperreflexia. "Finally, Btbd7 is involved in tissue remodelling of embryonic epithelial cells by interacting with cell-cell adhesion proteins, and is associated with preeclampsia in humans." (PMID 31349784, 2019).
squamous cell carcinoma (1 paper, 2014). A carcinoma arising from squamous epithelial cells. "Higher Btbd7 expression was found in adenocarcinomas compared to squamous cell carcinomas (p < 0.05)." (PMID 25253020, 2014).
tumor (10 papers, 2014 to 2025). "Meanwhile, BTBD7 was found highly expressed in tumor tissues of NSCLC patient and associated with poor prognosis." (PMID 33108235, 2020). "We examined E-cadherin and N-cadherin expression in NSCLC and non-tumor lung portions using IHC and analyzed their association with Btbd7 expression." (PMID 25253020, 2014). "BTBD7-SLC2A5 may be involved in unregulated cell adhesion, motility and epithelial morphogenesis due to loss of exons 10 and 11 of BTBD7, or be involved in shifting of energy metabolism to enhance tumor growth due to containing entire transmembrane domain and fructose transport domain of SLC2A5." (PMID 33391440, 2021). "The antimigration activity of ART is mediated by inhibition of BTBD7 mRNA expression while BTBD7 was found highly expressed in tumor tissues of NSCLC patients." (PMID 39525639, 2024). "BTBD7 bears various functions in the biological process of eukaryotic cell, including tissue and organ development, protein degradation, and tumor initiation and progression." (PMID 35655918, 2022). "BTBD7 predicts low recurrence and represses tumor progression by inactivating Notch1 signaling in BC." (PMID 35655918, 2022). "We identified 15, 12, 15, and 12 reads from tumor samples 306, 409, 206 and 815, in which at least 25 nts mapped in the genes for both BTBD7 and SLC2A5." (PMID 33391440, 2021). "A BTB/POZ family member, BTBD7, was highly expressed in HCC cells and tumor and was associated with enhanced cell motility, venous invasion, and poor prognosis." (PMID 33109073, 2020). "BTBD7 was first reported in 2001 as a liver cancer-related gene that promotes cell proliferation and tumor formation." (PMID 31886230, 2019). "Collectively, POLA2 overediting stimulates PCa tumor growth in vivo by upregulating BTBD7." (PMID 40366506, 2025). "Moreover, BTBD7 inhibits BC cell proliferation, invasion, migration, and tumor metastasis by inactivating the Notch1 pathway." (PMID 35655918, 2022). "We performed immunohistochemistry (IHC) analysis and Western blotting study to investigate Btbd7 expression in NSCLC and corresponding non-tumor lung tissues." (PMID 25253020, 2014). "Data from TCGA database showed that patients with high BTBD7 expression had a poor prognosis in overall survival, and immunohistochemical staining carried out in all 87 paired HCC sample also confirmed that BTBD7 was highly expressed in tumor tissues of NSCLC." (PMID 33108235, 2020).
cancer (4 papers, 2014 to 2022). A tumor composed of atypical neoplastic, often pleomorphic cells that invade other tissues. "BTB/POZ domain-containing protein 7 (BTBD7) BTBD7 regulates the dynamics of cell adhesion and motility during epithelial branching morphogenesis 58, and has been reported to be associated with various cancers 59-61." (PMID 33391440, 2021). "Our further study shows that downregulation of Btbd7 in NCI-H1299 cells significantly upregulated E-cadherin expression in cancer cells." (PMID 25253020, 2014). "Higher expression of Btbd7 was also found in cancer with advanced TNM stages (III + IV) (p < 0.05)." (PMID 25253020, 2014). "The data also indicate that Btbd7 may contribute to cancer development and patients’ poor clinical outcome through regulation of E-cadherin and cancer cell dynamics." (PMID 25253020, 2014). "Disorders of cell adhesion are critical steps in cancer progression in which varieties of markers including cadherins are involved in.Btbd7 was found to inhibit E-cadherin expression in MDCK cells and play important roles during branching morphogenesis of embryonic salivary glands and lungs." (PMID 25253020, 2014). "Our study shows that Btbd7 is required for cancer cell invasion." (PMID 25253020, 2014). "However, how exactly Btbd7 functions in this malignant tumor still needs further investigation." (PMID 25253020, 2014). "So far, expression of Btbd7 and its function in malignant tumors are largely unknown." (PMID 25253020, 2014). "Western blotting study shows that downregulation of Btbd7 in NCI-H1299 cells significantly upregulated E-cadherin expression and downregulated snail 2 (slug), MMP2 and MMP7 expression in cancer cells." (PMID 25253020, 2014). "Actually there is a report about Btbd7 mRNA expression in hepatocarcinoma indicating a role of Btbd7 to promote cancer cell proliferation though mechanism involved was not mentioned and not clear." (PMID 25253020, 2014).
BTBD7 also shares sentences with these, for which no sentence is quoted: adenocarcinoma (1 paper); breast carcinoma (1); cardiovascular diseases (1); glioma (1); prostatic cancer (1).